ATF4 (activating transcription factor 4)
Diseases named in the same sentence as ATF4 in open-access papers (continued):
Sharing a sentence is not in itself a finding about the gene and the disease.
cancer (408 papers, 2005 to 2026). A tumor composed of atypical neoplastic, often pleomorphic cells that invade other tissues. "Dysregulation of this dichotomous function has been implicated in a variety of diseases, such as cancer, neurodegenerative disease, metabolic disease, etc., highlighting ATF4 as a potential therapeutic target." (PMID 41561820, 2026). "Mechanistically, the increase in CHAC1 expression in cancer cells can be linked to the induction of ferroptosis through the ATF4 mediated UPR branch." (PMID 41488051, 2025). "Active PERK/ATF4 signaling appeared to be strongly correlated with EMT-associated gene expression in human patient samples originating from different cancers, including breast cancer, colon cancer, gastric cancer, and lung cancer." (PMID 40001551, 2025). "When cancer cells sense glutamine deprivation or inhibition of glutamine metabolism, it causes cancer cell stress, triggering an increase in ATF4 transcription." (PMID 40598593, 2025). "For instance, cisplatin upregulates ATF4 expression, and ATF4-deficient cancer cells exhibit elevated sensitivity to cisplatin-induced cell death." (PMID 39261452, 2024). "Then we explored the expression profile of genes relevant to ATF4 signaling and evaluated the association between ATF4 signaling score and the prognosis of cancer patients." (PMID 39139391, 2024). "ATF4-mediated protection against reactive oxygen species (ROS) has also been linked to radio- and chemotherapy resistance in various cancer cells, including those derived from NSCLCs." (PMID 38672243, 2024). "In pancreatic ductal adenocarcinoma (PDAC), TGF-β1 secreted from cancer-associated fibroblasts (CAFs) drives the elevation of ATF4 expression through the SMAD2/3 pathway to modulate cancer cell proliferation, migration and stemness." (PMID 39261452, 2024). "They found that the deaths of the PAM-treated cancer cells were linked to excessive ROS accumulation in the mitochondria leading to the up-regulation of ATF4/CHOP activity." (PMID 38002354, 2023). "Its pro-survival function causes ATF4 to be a powerful oncogene, enabling cancer cells to form tumors despite oxidative and nutrient stress." (PMID 36869665, 2023). "Spautin-1 prevented the induction of UPR-associated proteins, including glucose-regulated protein 78, activating transcription factor 4, and a splicing variant of x-box-binding protein-1, and showed preferential cytotoxicity in glucose-starved cancer cells." (PMID 35798783, 2022). "Growing evidence suggests that a pro-survival role of ATF4 is to regulate gene-encoding proteins important for the elevation of glutamine metabolism in cancer, although in certain contexts ATF4 can also trigger cell death." (PMID 35963851, 2022). "In particular, the inability of cancer cells to activate the ATF4/CHOP pathway was a constant feature of THEM6‐deficient PCa cancer cells, irrespective of their AR status." (PMID 35014179, 2022). "Loss of ATF4 suppresses cancer progression, suggesting its critical role in their survival by maintaining amino acid pools in cancer cells." (PMID 34862383, 2021). "In this regard, p62 has also been shown to directly bind ATF4 and to modulate its stability in stromal fibroblasts, which is central to the ATF4-mediated metabolic reprogramming of cancer-associated fibroblasts to control tumorigenesis." (PMID 34001883, 2021). "ATF4 overexpression was found to be associated with tumorigenesis in a variety of cancers, including BC." (PMID 34185683, 2021). "Oncogenic signals, including Myc, PIK3CA hotspot mutations (H1047R and E545K) and KRAS hotspot mutation (G12V), upregulate ATF4 to promote cancer survival." (PMID 31064130, 2019). "The strongly predicted upstream drivers for the MCF-7 GRIP dataset included mainly cancer drivers (MYC, KMT2A) and cancer associated genes (ATF4)." (PMID 27097319, 2016).
cancer (continued). "Elevated expression of ATF4 in cancer cells has been associated with resistance to some chemotherapeutic drugs, such as DNA-damaging agents and proteasome inhibitors." (PMID 25680860, 2015). "Consequently, the ATF4-Gln metabolic axis represents a critical target for understanding the mechanisms underlying cancer initiation and progression." (PMID 40830338, 2025). "Mechanistically, lipid peroxidation‐ATF4‐Parkin pathway‐mediated mitophagy limits lipid peroxidation to halt ferroptosis in cancer, and mitophagy deficiency strongly increases lipid peroxidation and enhances ferroptosis induced by erastin, RSL3, cysteine deprivation, radiotherapy or immunotherapy." (PMID 39679775, 2025). "The ATF4 signaling score was detected to be positively associated with multiple pan-cancer malignant pathways, such as MYC targets, mTORC1, TNF-α signaling via NF-κB, DNA repair, hypoxia, and IL6/JAK/STAT3 signaling, while it was negatively associated with Notch and Wnt/β-catenin signaling." (PMID 39139391, 2024). "Our next step was to investigate how DT-061 could cause cancer cells to chronically activate ATF4 and CHOP, even after drug washout." (PMID 39349971, 2024). "Dysregulation of ATF4 expression has been implicated in various types of cancer." (PMID 39261452, 2024). "ATF4 has been implicated in various biological processes and diseases, including cellular stress response, development, cancer and metabolic diseases, and similarly, we found that the SNPs which reside in the chromatin binding sites of ATF4 are associated to a broad range of traits." (PMID 37906604, 2023). "Overall, BT2 recapitulated the effects of EAAm on cancer cells, thus suggesting that activation of BCAA catabolism may underlie the mixture's effects on glycolysis, ATF4 expression, mTORC1 signalling, and cancer cell death." (PMID 35367410, 2022). "To confirm that apoptosis of cancer cells was also associated with inhibition of mTORC1 signalling and ATF4 upregulation, we analysed phosphorylation of p70Ss kinase and the expression of ATF4 protein in M14 and Hela cells." (PMID 35367410, 2022). "Overexpression of ATF4 is suggested to enhance the susceptibility of cancer cells to ferroptosis." (PMID 35372041, 2022). "Furthermore, up-regulation of CHOP and ATF4 expression by ER stress was associated with sensitization to anti-cancer drug-induced apoptosis in ZFL-treated cancer cells." (PMID 30120227, 2018). "Moreover, this association between a low level of ATF4 protein and the resistance to amino acid deprivation was also observed in the cancer cell line BxPC-3." (PMID 28460466, 2017). "Furthermore, since AKT inhibition promotes autophagy during cancer cell death, we investigated whether the genes associated with autophagy, including Atg3, Becn1, and Atf4, were upregulated or downregulated using qPCR." (PMID 38732133, 2024). "Indeed, since ATF4 expression may be associated with cancer cell resistance to ERA, particularly in MiaPaCa-2 cells, its decreased expression at a later time point fits well with the highest levels of cell death observed." (PMID 37260977, 2023). "Moreover, ATF4 has been implicated in cancer progression and drug resistance." (PMID 34437475, 2021). "Interestingly, ATF4 has also been implicated in cancer progression." (PMID 31738790, 2019). "Additionally, the upregulation of ATF4 has been shown to modulate matrix metalloproteinases in esophageal squamous carcinoma, promote metastasis, and be closely associated with poor prognosis in cancer patients." (PMID 31739582, 2019). "As the synergistic effect of CLOCK and ATF4 has been implicated in multidrug resistance through glutathione-dependent redox system, a breakdown in this correlation could lead to differential drug response in human cancer." (PMID 26539209, 2015).
cancer (continued). "Stress-induced acute ATF4 expression occurs in diverse mammalian cell types and is typically protective; however, chronic activation contributes to pathologies including cancer and neurodegeneration." (PMID 41597261, 2026). "Beyond metabolic adaptation, the ATF4-glutamine axis contributes to several hallmarks of cancer, including resistance to cell death, enhanced metastatic potential, and immune evasion." (PMID 40830338, 2025). "Further studies are needed to functionally explore and precisely determine the role of the eIF2α-ATF4 signaling pathway in the liver during cancer progression, upon induction and evolution of cachexia." (PMID 40124481, 2025). "A similar effect is observed with Tanshinone IIA, which promotes DR5 expression via PERK/ATF4/CHOP activation, increasing cancer cell susceptibility to TRAIL-mediated apoptosis (Kim EO." (PMID 41476609, 2025). "Several key proteins interacting with ATF4 such as NRF2, GPX4, SLC7A11, PDIA4 have been suggested as mediators of the role ATF4 plays in preventing ferroptosis in various cancer models." (PMID 40667288, 2025). "While ATF4 expression is generally low in normal cells, it becomes markedly elevated in cancer cells, where it drives pathological processes." (PMID 41019540, 2025). "Later, it was shown that ONC201 induces endoplasmic reticulum (ER) stress response or integrated stress response (ISR) in various cancer types, which culminate through ATF4 activation." (PMID 40305155, 2025). "Understanding the intricate interplay between ATF4, Gln metabolic processes, and cancer progression provides valuable insights for novel therapeutic strategies." (PMID 40830338, 2025). "For cancers resistant to paclitaxel, targeting the EIF2α and ATF4 pathways mitigates drug resistance." (PMID 41301006, 2025). "Upon encountering ERS, ATF4 undergoes selective translation to increase the production of substances that promote the survival of cancer cells under stressful conditions." (PMID 40255561, 2025). "With continued research and the integration of precision medicine approaches, targeting the ATF4-Gln axis holds significant potential to transform cancer treatment paradigms and improve patient outcomes." (PMID 40830338, 2025). "As a key regulator of the integrated stress response (ISR), ATF4 equips cancer cells with enhanced survival and adaptation capabilities by modulating Gln metabolic processes and the expression of related genes in response to nutrient and oxidative stress." (PMID 40830338, 2025). "Recent studies have unveiled novel mechanisms by which ATF4 regulates glutamine metabolism across various cancer contexts." (PMID 40830338, 2025). "Previous studies showed that restricting glutamine activates the GCN2/eIF2α/ATF4 pathway in cancer cells." (PMID 41101503, 2025). "Mechanistically, we found that cancer cells activated mitophagy through the lipid peroxidation–ATF4–Parkin pathway to limit the generation of lipid peroxidation products, thereby inhibiting the occurrence of ferroptosis." (PMID 39679775, 2025). "In conclusion, the data presented above collectively indicate that PERK/ATF4 signaling can promote metastatic cancer spread by both increasing cell survival and directly upregulating the cellular enzymes involved in the cell migratory and invasive processes." (PMID 40001551, 2025). "For example, the activation of ATF4 expression in cancer cells inhibits the AKT/mTOR signaling pathway, leading to cell cycle arrest and autophagy." (PMID 40416391, 2025). "When exposed to ERS, ATF4 selectively undergoes translation to boost the expression of molecules that support the adaptive survival of cancer cells, notably SLC7A11/xCT3." (PMID 40255561, 2025). "ATF4 knockdown reduced cell viability under glutamine-deprived conditions, indicating that ATF4-mediated stress responses supported cancer cell survival." (PMID 40223274, 2025).
cancer (continued). "Activate PERK/eIF2α axis, inducing cancer cell apoptosis by targeting microtubules; resistance can be mitigated by targeting EIF2α/ATF4 pathway." (PMID 41301006, 2025). "For example, the cardiotoxic cancer drug ponatinib was found to activate the GCN2/eIF2α/Atf4 signaling axis in hiPSC-CMs and ISRIB was protective against cardiomyocyte death." (PMID 41101503, 2025). "Among these, artesunate, sevoflurane, dihydroartemisinin, brusatol, nisin, hederagenin, glaucocalyxin A, nootkatone, cannabinoids and ophiopogonin B successfully promote ferroptosis in diverse cancer cell types mediated by the ER stress branch ATF4-CHOP-CHAC1." (PMID 41488051, 2025). "ATF4 has emerged as a promising therapeutic target for the treatment and prevention of various diseases, with particular relevance in cancer research." (PMID 41019540, 2025). "The ATF4-Gln metabolic processes axis is increasingly recognized as a key participant in cancer cell metabolic reprogramming." (PMID 40830338, 2025). "In contrast, mitochondrial ROS remained stable throughout the entire process of ferroptosis induction and did not significantly increase even at the late stage of ferroptosis induction in ATF4‐overexpressing cancer cells compared with wild‐type cancer cells." (PMID 39679775, 2025). "The apoptotic phenotype observed in vivo and in vitro under Macrocarpal I treatment further experimentally validated that Macrocarpal I promotes cancer cell apoptosis through activating the PERK/eIF2a/ATF4/CHOP signaling pathway." (PMID 39987121, 2025). "Previous research has shown that the EAA mixture inhibits mTORC1 and activates ATF4, ER-stress, and apoptotic pathways specifically in cancer cells." (PMID 40725262, 2025). "It has been shown that cancer cells activate the PERK-eIF2α-ATF4 axis to mediate hypoxia tolerance, translation of angiogenic factors, upregulation of autophagy genes, and crosstalk with the HIF pathway." (PMID 41228326, 2025). "The PERK/ATF4/LAMP3-arm mediates hypoxia-induced cancer cell migration, indicating that inhibiting this axis can result in the radiosensitization of BRCA cells." (PMID 41450825, 2025). "The data revealed that knockout of ATF4 significantly attenuated the mRNA and protein levels of Parkin in cancer cells under physiological and erastin or RSL3 or cystine deprivation treatment conditions." (PMID 39679775, 2025). "Collectively, these findings suggest that COP reduces ATF4 levels, thereby diminishing stress‐induced cancer cell survival." (PMID 38994891, 2024). "Here, we show that shRNA-mediated depletion of ALKBH5 or FTO (using a lentiviral system) significantly decreased ATF4 protein levels in SOR-treated Hep3B cancer cells." (PMID 39199320, 2024). "In fact, ATF4 has been well-accepted as a stress-induced transcription factor to selectively upregulate the downstream genes for cancer progression and drug resistance." (PMID 39090107, 2024). "Meanwhile, miR-214 enhances the effects of erastin and by inhibiting the expression of activating transcription factor 4 (ATF4) in HepG2 and Hep3B cancer cells." (PMID 39600338, 2024). "ATF4 showed a dual role in iron death and cancer under endoplasmic reticulum stress, and under sustained stress conditions, ATF4 promotes apoptotic cell death induction." (PMID 39430754, 2024). "ATF4 overexpression in solid tumors is crucial for their survival in various mouse and human cancers, and targeting ATF4 for elimination induces apoptosis in cancer cells." (PMID 39691874, 2024). "Induction of an ER‐stress response in autophagy‐dependent cancer cells inhibits cell proliferation by upregulating the transcription factor ATF4." (PMID 38414326, 2024). "Using actinomycin D (ActD), a potent transcription inhibitor, we found that in both cancer and normal cell lines, ActD inhibits DT-061-stimulated mRNA levels of ATF4 and all its downstream targets." (PMID 39349971, 2024). "These opposite effects underscore the intricacy of the role of GCN2, and ATF4 in cancer cell growth." (PMID 39013537, 2024).
cancer (continued). "The formation of this stable complex disrupts the interaction between transcription factor AP‐2 alpha (TFAP2A) and ATF4‐G4, resulting in a substantial reduction in intracellular ATF4 levels and the eventual death of cancer cells." (PMID 38994891, 2024). "Reactive oxygen species (ROS) induced by hypoxia promote endoplasmic reticulum (ER) stress to activate PERK-eIF2α-ATF4 axis in cancer cells." (PMID 39079386, 2024). "Cellular investigations confirmed that a single dose of radiation‐induced an elevation in iMOMP in cancer cells, resulting in a significant upregulation of p‐eIF2α and ATF4." (PMID 38520732, 2024). "In the context of cancer, the inhibition of key UPRmt regulators, such as ATF5, ATF4, and SIRT, has been linked to cancer growth and progression." (PMID 39771153, 2024). "We demonstrated that COP significantly reduced the expression of ATF4 induced by glutamine restriction, leading to substantial inhibition of cancer cell proliferation." (PMID 38994891, 2024). "ATF4 expression is frequently elevated in cancer and induced by factors in the tumor microenvironment that drive cancer progression." (PMID 38247494, 2024). "Inhibition of TFAP2A reduced ATF4 expression and suppressed cancer cell proliferation in the presence of 0.25 mM glutamine." (PMID 38994891, 2024). "In summary, the selective cytotoxicity of VCP inhibition towards cancer cells can be attributed to the disruption of proteotoxic stress mitigation pathways involving the ATF4/DDIT4 axis and hyperactive mTORC2/Akt signaling." (PMID 38218922, 2024). "Glutamine deprivation triggers metabolic adaptation, leading to the emergence of cancer persister cells that rely on stress‐induced ATF4 transcriptional reprogramming." (PMID 38994891, 2024). "In cancers, ATF4 has been identified as a stress-induced transcription factor and found to be frequently upregulated in a series of tumors." (PMID 38601083, 2024). "In the clinical cohort, 23% of cancer patients had high levels of ATF4 expression during glutamine depletion." (PMID 38994891, 2024). "It was established that the PERK-eIF2α-ATF4 pathway activation promotes angiogenesis, invasion, and epithelial–mesenchymal transition, thereby increasing the metastatic potential in various cancers, including NSCLC." (PMID 38672243, 2024). "mTOR and ATF4 have been widely studied for their important roles in regulating oncogenic proliferation and cancer cell survival." (PMID 38424194, 2024). "This review primarily aims to elucidate the functions of ATF4 and its role in multiple cancer contexts." (PMID 38601083, 2024). "As a stress-induced transcription factor, ATF4 controls the expression of a wide range of adaptive genes which allow cancer cells to endure periods of stress." (PMID 39090107, 2024). "Given the involvement of deregulated ATF4 expression in various pathologies and cancers, the complexity of its translational control should be kept in mind when considering therapies directed against this potent regulator of cell life or death." (PMID 38507410, 2024). "Glutamine restriction triggered ATF4 translational reprogramming, which accounted for over 50% of persister cancer cell survival and weakened the efficacy of glutamine‐deficient therapy." (PMID 38994891, 2024). "Cell viability data and death marker protein expression show that the loss of ATF4, TFE3, or the combination of the two can significantly abrogate DT-061 effects on cancer cell death." (PMID 39349971, 2024). "In cancer cells, the level of ATF4 mRNA translation induced by p-eIF2α is critical to promote either cell death or survival to ER stress generated upon treatment with genotoxic drugs." (PMID 39199320, 2024). "Depletion of ATF4 increases sensitivity in certain cancer cells, while its knockdown enhances ferroptosis induction in others." (PMID 39104501, 2024).